PTPN6 (protein tyrosine phosphatase non-receptor type 6)
Description:
Tyrosine phosphatase enzyme that plays important roles in controlling immune signaling pathways and fundamental physiological processes such as hematopoiesis. Dephosphorylates and negatively regulate several receptor tyrosine kinases (RTKs) such as EGFR, PDGFR and FGFR, thereby modulating their signaling activities. When recruited to immunoreceptor tyrosine-based inhibitory motif (ITIM)-containing receptors such as immunoglobulin-like transcript 2/LILRB1, programmed cell death protein 1/PDCD1, CD3D, CD22, CLEC12A and other receptors involved in immune regulation, initiates their dephosphorylation and subsequently inhibits downstream signaling events. Modulates the signaling of several cytokine receptors including IL-4 receptor. Additionally, targets multiple cytoplasmic signaling molecules including STING1, LCK or STAT1 among others involved in diverse cellular processes including modulation of T-cell activation or cGAS-STING signaling. Within the nucleus, negatively regulates the activity of some transcription factors such as NFAT5 via direct dephosphorylation. Also acts as a key transcriptional regulator of hepatic gluconeogenesis by controlling recruitment of RNA polymerase II to the PCK1 promoter together with STAT5A.
Synonyms: PTP-1C; HCP; HCPH; SHP-1; SHP1; HPTP1C; SH-PTP1; SHP-1L
Tractability: Small molecule: a high-quality ligand is known; it has a binding pocket of medium quality. Antibody: its Gene Ontology location is reachable by antibodies, with high confidence. PROTAC: UniProt records ubiquitination sites on it; ubiquitination databases record sites on it; its protein half-life has been measured; a small molecule that binds it is known.
Target class: Tyrosine protein phosphatase; Enzyme; Phosphatase; Protein Phosphatase
Gene: Protein-coding gene on chromosome 12 (6,946,417 to 6,961,316, forward strand). Ensembl gene ENSG00000111679.
Subcellular location: Cytoplasm; Nucleus
Subcellular location (Human Protein Atlas): Nucleoplasm; Nucleoli
Pathways (Reactome):
Immune System: Antigen activates B Cell Receptor (BCR) leading to generation of second messengers; CD22 mediated BCR regulation; Co-inhibition by BTLA; Co-inhibition by PD-1; Growth hormone receptor signaling; Interferon alpha/beta signaling; Interferon gamma signaling; Interleukin receptor SHC signaling; Interleukin-3, Interleukin-5 and GM-CSF signaling; Interleukin-37 signaling; Neutrophil degranulation; Regulation of IFNA/IFNB signaling; Regulation of IFNG signaling
Hemostasis: GPVI-mediated activation cascade; PECAM1 interactions; Platelet sensitization by LDL
Disease: Nuclear events stimulated by ALK signaling in cancer; SARS-CoV-2 activates/modulates innate and adaptive immune responses
Signal Transduction: Regulation of KIT signaling; Signaling by ALK
Cell-Cell communication: Signal regulatory protein family interactions
Gene Ontology:
Molecular function: phosphorylation-dependent protein binding; phosphotyrosine residue binding; protein binding; protein kinase binding; protein tyrosine phosphatase activity; transmembrane receptor protein tyrosine phosphatase activity; non-membrane spanning protein tyrosine phosphatase activity; cell adhesion molecule binding; SH2 domain binding; SH3 domain binding
Biological process: CD27 signaling pathway; cell differentiation; negative regulation of angiogenesis; negative regulation of B cell receptor signaling pathway; negative regulation of inflammatory response; negative regulation of inflammatory response to wounding; negative regulation of innate immune response; negative regulation of neutrophil activation; peptidyl-tyrosine dephosphorylation; peptidyl-tyrosine phosphorylation; positive regulation of cell population proliferation; positive regulation of phosphatidylinositol 3-kinase/protein kinase B signal transduction; protein dephosphorylation; regulation of ERK1 and ERK2 cascade; regulation of G1/S transition of mitotic cell cycle; T cell activation; cytokine-mediated signaling pathway; G protein-coupled receptor signaling pathway; mitotic cell cycle; negative regulation of cell population proliferation; negative regulation of interleukin-6 production; negative regulation of lipopolysaccharide-mediated signaling pathway; negative regulation of tumor necrosis factor production; regulation of type I interferon-mediated signaling pathway; T cell costimulation; and 3 more
Cellular component: cytoplasm; extracellular exosome; nucleolus; nucleoplasm; nucleus; plasma membrane; protein-containing complex; cytosol; extracellular region; membrane; specific granule lumen; tertiary granule lumen; alpha-beta T cell receptor complex; cell-cell junction
Genetic constraint (gnomAD): Loss-of-function variants: 18 observed, 82.22 expected, observed/expected ratio (o/e) 0.22, 90% interval 0.15 to 0.32. The upper end of that interval is the gene's LOEUF score, 0.32, which puts it in group 1 of 6, group 1 being the genes least tolerant of losing a copy. Missense variants: 499 observed, 817.66 expected, observed/expected ratio (o/e) 0.61, 90% interval 0.57 to 0.66. Synonymous variants: 301 observed, 320.69 expected, observed/expected ratio (o/e) 0.94, 90% interval 0.85 to 1.03.
Homologues: Orthologues: chimpanzee PTPN6 (99% identical), macaque PTPN6 (98% identical), pig PTPN6 (96% identical), dog PTPN6 (96% identical), guinea pig PTPN6 (95% identical), mouse Ptpn6 (94% identical), rat Ptpn6 (94% identical), rabbit PTPN6 (90% identical), zebrafish ptpn6 (65% identical), tropical clawed frog ptpn6 (62% identical). Paralogues in human: PTPN11 (54% identical), PTPRS (30% identical), PTPRK (30% identical), PTPRT (29% identical), PTPRM (29% identical), PTPRZ1 (28% identical), PTPRF (28% identical), PTPRD (28% identical), PTPRG (28% identical), PTPRJ (26% identical), PTPRU (26% identical), PTPRB (25% identical), and 23 more.
Diseases named in the same sentence as PTPN6 in open-access papers:
PTPN6 is named in the same sentence as 138 diseases in open-access papers, as found by Europe PMC text mining. Sharing a sentence is not in itself a finding about the gene and the disease. The quoted sentences say what the papers report.
breast carcinoma (10 papers, 2015 to 2024). "PTPN6 gene expression is downregulated in advanced chronic myelogenous leukemia, breast cancer, and liver cancer." (PMID 35186080, 2022). "PTPN6 dampens the oncogenic characteristics of breast cancer by dephosphorylating STAT3 and inactivating the Ras/extracellular signal-regulated kinase (Erk)/glycogen synthase kinase-3beta (GSK-3β) signaling pathway." (PMID 35957898, 2022). "SNAI2 is a direct target of the glucocorticoid receptor GR that regulates cell migration in breast cancer, while PTPN6 is involved in glucose homeostasis via negative regulation of insulin signalling." (PMID 33513136, 2021). "The low expression of PTPN6 was significantly associated with poor overall survival in bladder cancer patients and co-expression with TNFRSF14 (tumor necrosis factor receptor superfamily member 14) had a close correlation in breast cancer." (PMID 34163522, 2021). "Furthermore, the remarkable association between pri-miR-200c-141 and pri-PTPN6 transcription was not restricted to stress conditions but also observed at basal state in ovarian and breast cancer cell lines." (PMID 26725650, 2016). "In light of our results, we propose that PTPN6, a tumour-suppressor gene in leukaemia and lymphoma, acts as a fibrotic suppressor gene in CAF from head and neck, lung and breast cancers." (PMID 26667266, 2015). "However, most PTPN family members function as tumor suppressors in breast cancer, including PTPN2, PTPN4, PTPN6, PTPN9, PTPN13, PTPN14, and PTPN23." (PMID 35957898, 2022).
hepatocellular carcinoma (9 papers, 2020 to 2024). A malignant tumor that arises from hepatocytes. "Previous studies indicated that PTPN6 was associated with the prognosis and progression of cancers, such as hepatocellular carcinoma, renal cell carcinoma, and gastric cancer." (PMID 32454905, 2020). "Indeed, loss of PTPN6 is associated with poor prognosis in hepatocellular carcinoma (HCC), whilst in healthy hepatocytes and HCC cell lines, PTPN6 inhibits the JAK-STAT, nuclear factor (NF)-κB and Akt-dependent signalling pathways." (PMID 38334623, 2024). "To validate the effects of SHP-1 on PCK1 transcription in another liver cell line, we used Ptpn6 shRNA to knockdown Ptpn6 by about 50% in FAO rat hepatoma cells as compared to the control shRNA." (PMID 37595871, 2023). "Existing research found that PTPN6 is correlated with cancers like hepatocellular cancer, renal cell cancer, and gastric cancer's prognosis and progression." (PMID 36211821, 2022). "Additionally, PTPN6, through the SHP-1/JAK2/STAT3 signaling pathway, plays an important role in the treatment of osteosarcoma, hepatocellular carcinoma, and leukemia." (PMID 39590309, 2024).
leukemia (8 papers, 2015 to 2024). A malignant (clonal) hematologic disorder, involving hematopoietic stem cells and characterized by the presence of primitive or atypical myeloid or lymphoid cells in the bone marrow and the blood. "Noteworthy pre-clinical studies showcased the benefits of transferring PTPN6 knockout T cells in leukemia models." (PMID 38023180, 2023). "Among those relative upregulated genes, PTPN6, which had been confirmed to play a crucial role as a cancer suppressor in leukemia, was focused on." (PMID 34295818, 2021). "The findings showed that PTPN6, PTPN18, and PTPN22 had higher expression levels in leukemia than in normal blood samples, while PTPN1 had a lower expression level in the former than the latter." (PMID 36699453, 2022).
ovarian carcinoma (8 papers, 2016 to 2024). A malignant neoplasm originating from the surface ovarian epithelium. "PTPN6 mutations have been reported in several cancers; the total incidence of such mutations is 2.7% (uterine carcinosarcoma, 7.01%; testicular germ cell carcinoma, 6.04%; ovarian cancer, 5.82%; and melanoma, 5.18%)." (PMID 38203502, 2023). "PTPN1 and PTPN6 are highly expressed in ovarian cancer cell lines, in which PTPN1 accelerates ovarian cancer progression in a c-Jun N-terminal kinase (JNK)-dependent mechanism." (PMID 35957898, 2022). "A study performed in ovarian cancer cells indicated that miR-200c and miR-141 are co-expressed with the PTPN6 gene (coding for SHP1), which is located 5′ to the miR-200c/141 locus." (PMID 34884985, 2021). "We observed that the read-through from the PTPN6 gene is a dominant mechanism in ovarian cancer cells, each molecule of the pri-miR-200c-141 primary transcript corresponding to one molecule of bypassed PTPN6 polyadenylation signal." (PMID 26725650, 2016). "Its co-transcription with PTPN6 provides a potential way to target miR-200c in ovarian cancer." (PMID 34572448, 2021). "As expected, the PTPN6 haematopoietic promoter P2 is highly methylated in ovarian cancer cells." (PMID 26725650, 2016). "Taken as a whole, these results show that the transcriptional read-through from the PTPN6 gene leads to the transcription of the pri-miR-200c-141 and explains, at least in part, how PTPN6 transcription could regulate miR-200c/141 levels following oxidative stress in ovarian cancer cells." (PMID 26725650, 2016).
colon cancer (7 papers, 2020 to 2025). "High expression of PTPN6 is associated with poor prognosis in patients with colon cancer." (PMID 35186080, 2022). "Ptpn6-deficient BMDMs exhibited a 2–3-fold increase in phagocytic index compared to WT macrophages when co-cultured with DLD1 or Raji human cancer cells as well as the murine syngeneic colon tumor line MC38." (PMID 33133093, 2020). "Of note, PTPN6, a tyrosine phosphatase, affects cell growth and carcinogenesis in both bladder and colon cancer." (PMID 37895248, 2023). "Then, sh-NC and sh-PTPN6 treated colon cancer cells were implanted subcutaneously into the left anterior axilla of nude mice." (PMID 35186080, 2022). "Immunohistochemical results showed that the expression of PTPN6 protein in colon cancer tissue was consistent with the expression trend of PTPN6 mRNA." (PMID 35186080, 2022). "The results of scratch healing and transwell invasion assay showed that in vitro migration and invasion ability of colon cancer cells were significantly increased after transfection of PTPN6 overexpressing plasmid." (PMID 35186080, 2022). "In this study, the expression of PTPN6 gene in colon cancer cell lines was firstly confirmed by experiments." (PMID 35186080, 2022). "CCK-8, clone formation assay, scratch assay, and transwell assay were used to detect the effect of knockdown or overexpression of the PTPN6 gene on the malignant biological behavior of colon cancer cells." (PMID 35186080, 2022). "The high expression of the PTPN6 gene can promote the proliferation, migration, and invasion of colon cancer cells." (PMID 35186080, 2022). "The qPCR results showed that PTPN6 mRNA was expressed in colon cancer tissues in adjacent normal tissues." (PMID 35186080, 2022). "The results of CCK-8 and clone formation assay showed that the proliferation ability of colon cancer cells transfected with PTPN6 overexpressing plasmid was significantly enhanced in vitro." (PMID 35186080, 2022). "The PTPN6 gene may act as an oncogene in promoting colon cancer, and it also plays an important role in regulating colon cancer cell proliferation, migration, and invasion." (PMID 41154660, 2025). "PTPN6-EGFR complex may be an important factor affecting the biological characteristics of colon cancer cells and a potential therapeutic target." (PMID 35186080, 2022). "PTPN6 overexpression vector and siRNA knockdown were constructed and transiently transfected into human colon cancer cells, respectively, to investigate the effect of overexpression of the PTPN6 gene on proliferation, migration, and invasion of colon cancer cells in vitro." (PMID 35186080, 2022). "The expression level of PTPN6 mRNA in different colon cancer cell lines was detected by qPCR." (PMID 35186080, 2022). "The expression of PTPN6 protein was significantly increased in colon cancer tissues." (PMID 35186080, 2022). "In this study, we detected the expression of PTPN6 in different colon cancer cell lines." (PMID 35186080, 2022). "Clinical data analysis also showed that PTPN6 was highly expressed in colon cancer tissues." (PMID 35186080, 2022). "In conclusion, this study suggests that PTPN6 gene may be an oncopromoter gene in colon cancer." (PMID 35186080, 2022). "Protein tyrosine phosphatase non-receptor type 6 is a key regulatory protein in cell signaling that regulates cell death and inflammation; It has different regulatory mechanisms and effects on cell cycle and cell proliferation in different tumors and upregulated in colon cancer." (PMID 35957889, 2022). "In space, in order to further clarify the interaction between PTPN6 and EGFR, we performed immunofluorescence detection of PTPN6 and EGFR in colon cancer cells." (PMID 35186080, 2022). "In order to further detect the effect of sh-PTPN6 on the tumor-forming ability of SW480 cells, the xenograft tumor model of nude mice was established by injecting SW480 colon cancer cells subcutaneously." (PMID 35186080, 2022).
colon cancer (continued). "Mechanism studies showed that PTPN6 can interact with EGFR, which is expected to be a molecular target for the treatment of colon cancer." (PMID 35186080, 2022). "The results of qPCR method showed that the relative expression levels of PTPN6 mRNA in HCT-116, HCT-8, SW620, SW480, LOVO, and other colon cancer cells were significantly higher than those in the control group (HIEC-6)." (PMID 35186080, 2022). "This study investigates the expression of nonreceptor protein tyrosine phosphatase 6 (PTPN6) gene in different colon cancer cells and its effect on malignant biological behavior." (PMID 35186080, 2022).
glioma (7 papers, 2018 to 2024). A benign or malignant brain and spinal cord tumor that arises from glial cells (astrocytes, oligodendrocytes, ependymal cells). "More importantly, the gene expression of PTPN6 was significantly related to different glioma subtypes in TCGA and CGGA datasets." (PMID 37737713, 2023). "Our study employed a comprehensive analysis of publicly available datasets and functional experiments to assess PTPN6 gene expression, prognostic value, and related immune characteristics in glioma." (PMID 37737713, 2023). "In prostate cancer and high-grade glioma, PTPN6 promoter methylation and reduced expression of Shp1 correlate with increased malignancy and poor prognosis." (PMID 32596156, 2020). "In addition, the high expression of PTPN6 was mainly related to advanced grade and poor OS in glioma." (PMID 37737713, 2023). "The overexpression of PTPN6 was also found in the other four independent glioma datasets." (PMID 37737713, 2023). "Moreover, PTPN6 facilitated cell cycle progression, inhibited apoptosis, and promoted glioma cell proliferation, tumor growth, and colony formation in mice." (PMID 37737713, 2023). "Interestingly, a good correlation of PTPN6 methylation between cell-free circulating DNA from plasmas/sera and matched tumoral tissue is observed in glioma patients." (PMID 32596156, 2020). "PTPN6 expression was increased in glioma and its expression correlating with poor survival." (PMID 30220890, 2018). "Additionally, we observed that PTPN6 could inhibit cell apoptosis and promote tumor proliferation in glioma cell lines." (PMID 37737713, 2023). "Decreased Shp1 expression and PTPN6 hypermethylation are linked to tumor staging, pathological differentiation, and poor survival in various cancers, including esophageal squamous cell carcinoma (ESCC), endometrial carcinoma (EC), high-grade glioma (HGG), and NSCLC." (PMID 38022587, 2023). "However, THP-1 and HMC3 cells cultured in presence U87MG glioma demonstrated the opposite action of Dex and TMZ on PTPN6 transcript expression." (PMID 33670244, 2021). "Besides, the IHC confirmed that high levels of PTPN6 and PSMB8 expression occurred in glioma tissues." (PMID 35127714, 2021).
gastric cancer (6 papers, 2017 to 2024). A primary or metastatic malignant neoplasm involving the stomach. "In addition to this, we identified a candidate vaccine gene for gastric cancer: PTPN6." (PMID 35528539, 2022).
prostate carcinoma (6 papers, 2017 to 2024). A carcinoma that arises from epithelial cells of the prostate gland. "Another recent study reported that PTPN6 is capable of decreasing prostate cancer cell proliferation and enhancing apoptosis, thus revealing that it can be a potential therapeutic target for prostate cancer." (PMID 36211821, 2022). "PTPN6 can suppress growth and increase apoptosis in prostate cancer cells, which indicated that PTPN6 may be a novel therapeutic target in prostate cancer." (PMID 32454905, 2020). "WIN55212-2 increased the expression of several phosphatases including dual specificity phosphatases 1 and 10 (DUSP1, DUSP10) and protein tyrosine phosphatase, non-receptor type 6 (PTPN6) in LNCaP prostate cancer cells." (PMID 29066974, 2017).
acute myeloid leukemia (5 papers, 2016 to 2024). Acute myeloid leukemia (AML) is a group of neoplasms arising from precursor cells committed to the myeloid cell-line differentiation. "Some classical PTPs exhibited carcinogenic features, such as PTPN12 in PAAD and PTPN6 in acute myeloid leukemia (LAML)." (PMID 36341348, 2022). "In acute myeloid leukemia, editing in the putative branch site of tumor suppressor PTPN6 mRNA, which leads to aberrant intron retention, was suggested to account for PTPN6 functional insufficiency." (PMID 28009993, 2017). "Editing of the hematopoietic cell tyrosine phosphatase PTPN6 transcript is linked to acute myeloid leukemia (AML), but editing does not occur in the subgroup of AML with normal karyotype." (PMID 27999332, 2016). "Promoter methylation of PTPN6 occurs in acute myeloid leukemia (AML) cells; indeed, treatment with 5-Azacytidine (5-AZA), an inhibitor of the DNA methyltransferase (DNMT) 1, upregulated PTPN6, thereby resulting in STAT3 inhibition." (PMID 38534772, 2024).